ALB (albumin)
Diseases named in the same sentence as ALB in open-access papers (continued):
Sharing a sentence is not in itself a finding about the gene and the disease.
breast tumor (15 papers, 2008 to 2026). "Measurement values of albumin, condition of “hernia of abdominal wall,” and “neoplasm of breast” were negatively associated with prolonged hospital stay, while measurement values of total bilirubin, C reactive protein, and condition of osteitis were positively associated." (PMID 37955965, 2023). "Albumin-bound paclitaxel (PTX@Alb) accumulates in 4T1 breast tumors and reduces the expression of PD-L1 and TGF-β, resulting in enhanced T cell infiltration of the tumors." (PMID 41246345, 2025). "Exploiting different mechanisms of action, a novel triple drug delivery system of 5-fluorouracil, curcumin, and piperine co-loaded human serum albumin nanoparticles (5FU-CUR-PIP-HSA-NPs) was developed via the self‐assembly method for suppressing breast tumor." (PMID 36800370, 2023). "In this study, we developed a biocompatible bacteria/nanoparticles biohybrid (Bif@DOX-NPs) platform that employs the anaerobic Bifidobacterium infantis (Bif) to deliver adriamycin-loaded bovine serum albumin nanoparticles (DOX-NPs) into breast tumors." (PMID 35366890, 2022). "Furthermore, in vitro experiments have verified these findings, demonstrating that cordycepin enhances ALB expression in vitro and exhibits anti-breast tumor effects." (PMID 40601671, 2025). "In this work, a novel triple drug delivery system of 5-fluorouracil, curcumin, and piperine co-loaded human serum albumin nanoparticles (5FU-CUR-PIP-HSA-NPs) was synthesized via the self‐assembly method to impose a synergistic effect on breast tumor tissue with different mechanisms of action." (PMID 36800370, 2023). "In this study, bovine serum albumin (BSA)-coated gold nanorods (BSA-coated AuNRs) were prepared and used for photothermal ablation of breast tumor cells." (PMID 30583459, 2018). "Tumor vasculature of MCF-7 breast tumor mouse xenografts was studied by a combination of MR angiography and DCE-MRI with albumin-Gd-DTPA." (PMID 24466160, 2014).
encephalitis (15 papers, 2018 to 2026). An acute inflammatory process affecting the brain parenchyma. "BBB impairment was described in animal models of encephalitis and is reflected by an increased cerebrospinal fluid (CSF) albumin concentration in patients in the clinical setting." (PMID 40003967, 2025). "The results of univariate regression analysis indicated that age, ethnicity, RBC, lymphocyte, ALB ALT, AST, bilirubin total, chloride, fibrinogen, and hospital LOS, were positively associated with encephalitis (all P < 0.05)." (PMID 41050284, 2025). "The purpose of this study was to investigate the association of neutrophil percentage-to-albumin ratio (NPAR) with the severity at admission and discharge (short-term prognosis) in patients with anti-N-methyl-D-aspartic acid receptor (NMDAR) encephalitis." (PMID 35479085, 2022). "Anti-NMDAR encephalitis was frequent in the low albumin group (11, 64.7%), and anti-LG1 encephalitis was frequent in the high albumin group (10, 66.7%)." (PMID 29343812, 2018). "This retrospective study aimed to investigate the relationship between fibrinogen-to-albumin ratio percentage (FARP) and disease severity and prognosis in patients with anti-N-methyl-D-aspartate receptor (anti-NMDAR) encephalitis." (PMID 36908596, 2023). "For the patients with anti-NMDAR encephalitis, the CSF WBC, protein, IgG, and albumin levels were also significantly higher in elevated Qalb group than those in normal Qalb group (all P < 0.05)." (PMID 36419157, 2022).
essential hypertension (15 papers, 2010 to 2025). Hypertension that presents without an identifiable cause. "The univariate analysis revealed that the TyG index, sex, age, ALB, HDL-C, AST, Scr, BUN, glucose, eGFR, ALT, LPa, and TG were associated with HUA in patients with primary hypertension (all P < 0.05)." (PMID 37360061, 2023).
gallstones (15 papers, 2013 to 2025). Solid crystalline precipitates in the biliary tract, usually formed in the gallbladder, resulting in the condition of cholelithiasis. "ALI integrates BMI, serum albumin level, and NLR—three key factors that are independently associated with gallstone risk—offering a comprehensive evaluation of the influence of inflammation and nutrition." (PMID 40233085, 2025). "Conversely, subjects with gallstones showed lower levels of albumin, creatinine, HDL-C, and total energy fat intake." (PMID 39574912, 2024). "A higher body mass index (BMI), total bilirubin, tumor size, and lower albumin were observed in the gallstone group." (PMID 36936662, 2023). "Significant differences in terms of the TG18 grade, albumin level, presence of gallstones, presence of CCVD, history of malignancy, and number of all-cause deaths were observed between the two groups." (PMID 34711183, 2021). "Ten gallstone disease variants associate with ALT, seven with AST, fourteen with GGT, nine with ALP, two with albumin, and two with bilirubin." (PMID 30504769, 2018). "Age, BMI, percentage of males, globulin:albumin ratio (G/A), percentage of patients with gallstones, AST, and ALT were significantly higher in the LD group." (PMID 27518399, 2016). "As IL-6 role in cholecystitis is stimulation of acute phase protein and albumin synthesis, as well as stimulation of B cells and immunoglobulin production, we speculate that IL-6 is a key interleukin of gallstone wall response to the inflammatory process." (PMID 34449702, 2021). "The ALI, composed of BMI, serum albumin levels, and NLR, can comprehensively reflect the role of inflammation and nutrition on gallstones." (PMID 40233085, 2025). "Albumin, as one of the indicators of nutritional status, was found to be statistically significant in our study in the difference between gallstone formers (3.95 ± 0.35) and non-gallstone formers (4.07 ± 0.34)." (PMID 39758317, 2024).
hypophosphatemia (15 papers, 2013 to 2025). Lower than normal levels of phosphates in the circulating blood. "Our findings revealed that hypophosphatemia (<4 mg/dL) was linked to an increased risk of CVD mortality in young patients with high serum TA albumin levels." (PMID 39385948, 2024). "Hypophosphatemia was linked to CVD mortality in patients aged <65 years with serum TA albumin levels >3.45 g/dL." (PMID 39385948, 2024). "Binary logistic regression analysis results revealed that the APACHE II score, male gender, serum albumin level, and hypophosphatemia were associated with ICU 28-day mortality, but age, serum potassium, serum calcium, and creatinine were not." (PMID 31122196, 2019). "We found that male sex, APACHE II scores, serum albumin level and hypophosphatemia were associated with 28-day mortality in the general ICU population." (PMID 31122196, 2019). "Even after adjustment for APACHE II scores and serum albumin, and the gender, hypophosphatemia (< 0.80 mmol/L) was still associated with increased 28-day mortality." (PMID 31122196, 2019). "After adjustment for APACHE II scores, serum albumin and gender, multivariable logistic regression analysis showed that hypophosphatemia was significantly associated with an increased risk of ICU 28-day mortality (OR = 1.5, 95% CI =1.1–2.1, P = 0.01)." (PMID 31122196, 2019). "Risk factors for hypophosphatemia included the following protective factors: higher albumin (OR 0.56, 95% CI 0.35-0.93), higher BUN (OR 0.90, 95% CI 0.86, 0.95), corrected calcium (OR 0.38, 95% CI 0.23-0.63) and female gender (OR 0.47, 95% 0.24-0.94)." (PMID 23965134, 2013). "Risk factors for hypophosphatemia included a lower albumin (p < 0.01), lower BUN (p=0.02), higher corrected calcium level (p < 0.01) and higher uric acid (p = 0.02)." (PMID 23965134, 2013). "Moreover, in our recently published study evaluating critically ill elderly patients with hypophosphatemia, low albumin once again emerged as an independent factor associated with ICU mortality." (PMID 40869586, 2025). "Patients with hypophosphatemia were likely to be older and with lower lymphocyte count, lower serum albumin level, lower uric acid, higher LDH, and higher CRP." (PMID 34541999, 2021). "Patients with hypophosphatemia were likely to be older and with lower lymphocyte count, lower serum albumin and uric acid levels, higher LDH, and CRP levels." (PMID 34541999, 2021). "In contrast, patients who developed hypophosphatemia during their hospital stay exhibited lower estimated glomerular filtration rate (eGFR), albumin, hemoglobin, and platelet levels, alongside elevated ferritin levels compared to those with hypophosphatemia at admission." (PMID 40183914, 2025). "Interestingly, significant association between hypophosphatemia and prolonged LOS was only found in patients with normal albumin or prealbumin concentration, which brought forth the proposal of screen for hypophosphatemia in well-fed patients." (PMID 39026252, 2024). "We found that a lower albumin level was presented in patients with hypophosphatemia." (PMID 34541999, 2021). "Laboratory investigations showed proteinuria (2+) with increased 24-hour UTP, albuminuria (elevated urine albumin and ACR), tubular proteinuria (LMW proteinuria and elevated urine α1-MG), hypercalciuria (increased urinary calcium to creatinine ratio [UCa/Ucr]), hypophosphatemia and hypokalemia." (PMID 33430795, 2021).
kernicterus (15 papers, 2009 to 2026). A term used pathologically to describe BILIRUBIN staining of the BASAL GANGLIA; BRAIN STEM; and CEREBELLUM and clinically to describe a syndrome associated with HYPERBILIRUBINEMIA. "Berberine is contraindicated during pregnancy and breastfeeding due to its ability to cross the placenta and displace bilirubin from albumin, posing a risk of kernicterus in newborns, and because it is excreted in breast milk." (PMID 40710568, 2025). "If the serum albumin concentration is low, the binding of bilirubin is less efficient, and the risk of kernicterus is increased." (PMID 33033449, 2020). "Another hypothesis is that certain TAPS donors have reduced albumin levels, which could lead to heightened bilirubin toxicity, potentially causing kernicterus and consequent impaired auditory functions." (PMID 38068261, 2023). "Alternative hypotheses that could also explain the TSB's poor predictive value for kernicterus include disrupted albumin/bilirubin binding capacity, reductions in available albumin, and use of TSB levels as the sole diagnostic test for bilirubin exposure." (PMID 27587993, 2016). "Bilirubin is an important biomarker, where a small unbound fraction dissociated from albumin can cross the blood-brain barrier and induce neurotoxicity, such as kernicterus, at low nanomolar levels." (PMID 42187478, 2026). "Moreover, serum albumin as a binding ligand for Bf represents a novel treatment for neonatal kernicterus." (PMID 34527681, 2021). "Bilirubin-induced neurological damage (BIND), which might progress to kernicterus, occurs as a consequence of defects in the bilirubin conjugation machinery, thus enabling albumin-unbound free bilirubin (BF) to cross the blood–brain barrier and accumulate within." (PMID 37759499, 2023). "However, it is becoming increasingly clear that the mechanisms involved in whether or not kernicterus occurs in newborns are much more complex than the absolute level of unconjugated bilirubin and the binding capacity of albumin in plasma." (PMID 25565938, 2014).
Multiple Organ Failure (15 papers, 2011 to 2025). A progressive condition usually characterized by combined failure of several organs such as the lungs, liver, kidney, along with some clotting mechanisms, usually postinjury or postoperative. "The lactate/albumin (L/A) ratio has been proposed as a prognostic marker because the ratio is associated with multiple organ failure and mortality in critically patients." (PMID 34691782, 2021). "The lactate/albumin (L/A) ratio has been proposed as a prognostic marker because the ratio is associated with multiple organ failure and mortality in critically ill patients." (PMID 34691782, 2021). "We hypothesized that a cumulative postoperative change in serum albumin until POD 5 was associated with the degree of multiple organ failure on POD 5 measured by the Sequential Organ Failure Assessment (SOFA) score." (PMID 37167307, 2023). "Conversely, the serum albumin level may reflect multiple organ failure caused by excessive levels of free water and reductions in protein metabolism." (PMID 31362417, 2019). "To exclude the possibility of multiple-organ failure, we conducted blood assessments of liver function markers, albumin (ALB) and alanine aminotransferase (ALT), in control versus Mdm2-cKO mice, showing no significant changes." (PMID 39946208, 2025). "Nevertheless, some studies have shown that albumin can help to improve outcomes and reduce multiple organ failure." (PMID 35694666, 2022). "Multiple organ failure is the source of circulating molecules, such as troponin, creatinine, and albumin, and circulating molecules have important value in the diagnosis of CS." (PMID 34957245, 2021). "TP and albumin levels, A/G ratio, and eGFR are also related to multiple organ failure." (PMID 34501223, 2021). "To overcome the limitations of previous studies, we investigated the association between the cumulative postoperative change in serum albumin up to postoperative day (POD) 5 and multiple organ failure only for recipients of LDLT." (PMID 37167307, 2023).
parasitic infection (15 papers, 2012 to 2025). "The sensitivity for detecting proteins associated with parasitic infections was low, ranging from 5.3% (gamma globulins) to 11.2% (albumin)." (PMID 41574255, 2025). "This is related to the lower serum albumin levels recorded in the same groups, which in turn are reduced because they are categorized as more susceptible to gastrointestinal parasitosis due to spoliation." (PMID 37570207, 2023). "This may be due to a combination of the selective loss of the smaller molecule albumin and an increase in globulin, as immunoglobulins are produced in response to inflammation caused by the parasite infection and tissue damage." (PMID 35625083, 2022). "The plasma ALP, albumin and hemoglobin showed good sensitivity to the increase in parasitemia since its reduction was related to moderated blood parasite loads (p <.05)." (PMID 35371021, 2022). "Clinical examination, determination of parasitemia, serum biochemistry (albumin, total protein, glucose, cholesterol, and urea), packed cell volume (PCV), serum progesterone, and pathological examination were performed." (PMID 23289625, 2013). "ALB is produced by the liver, reduced levels of this protein can point to chronic liver or kidney disease, or parasitic infections such as hookworm." (PMID 22754316, 2012). "As well as, the decline in serum TP and ALB levels besides the elevation in GLB levels might be a result of parasitic infection-induced stresses." (PMID 31528024, 2019). "Serum biochemical analyses revealed that the enzyme alkaline phosphatase continued to be significantly higher (p < 0.05) in R than S during the patent parasite infection, whereas the levels of albumin, cholesterol, globins, glucose, total proteins and urea remained similar between both groups." (PMID 29618989, 2018). "where ΔALB is the variation of albumin (g/L), ΔCREA is the variation of creatinine (μmol/L), ΔFERR is the variation of ferritin (ng/ml), ΔGHB is the variation of α-hydroxybutyrate dehydrogenase (U/L), Par is parasitemia (μl), and ΔUREA is the variation of urea (mmol/L)." (PMID 36439238, 2022). "Thus, the lower concentrations of albumin in the infected animals may be a result of acute-phase response as well due to gastrointestinal parasitic infection." (PMID 34888029, 2021). "In contrast, with increase in parasitemia rate, significant increase (P < 0.05) in WBC count and concentration of serum BUN, creatinine, total protein, albumin, globulin, triglyceride, cholesterol, HDL and LDL was evident." (PMID 25653743, 2012). "However, K98 also induced the de-differentiation of the HLCs and a decrease in the expression of the mature hepatocyte markers CYP3A4, Albumin and NTCP, and we hypothesize that this is the reason that we observe reduced parasite infection in K98-treated cells." (PMID 38770342, 2024). "Albumin’s role as a negative acute phase protein may contribute to reduced serum albumin levels in response to chronic parasitic infection." (PMID 35180232, 2022).
anorexia nervosa (14 papers, 2011 to 2026). A disorder most often seen in adolescent females characterized by a refusal to maintain a minimally normal body weight, an intense fear of gaining weight, a disturbance in body image, and, in postmenarcheal females, the development of amenorrhea. "In sum, the three variables, i.e., binge–purge behavior, a lower body mass index, and a lower serum albumin level, were associated with a lower serum potassium level at admission in patients with anorexia nervosa." (PMID 34362446, 2021). "In contrast, albumin and pre-albumin levels in serum are sustained when healthy individuals are severely deprived of nutrients and experience significant weight loss, either due to limited access to food or an unwillingness to eat, primarily because of anorexia nervosa." (PMID 35892736, 2022). "The mean admission albumin level for the anorexia nervosa patients was within normal limits (3.6 ± 0.7 g/dl, normal range 3-5.3 g/dl)." (PMID 21542928, 2011). "Similarly, another systematic review demonstrated that serum albumin and pre-albumin levels remained normal despite significant nutritional deprivation in patients with anorexia nervosa." (PMID 38817798, 2024). "Most patients with anorexia nervosa have normal serum albumin levels." (PMID 29026589, 2017). "Moreover, anorexia nervosa has traditionally been viewed as an illness with malnourishment, but devoid of a prominent inflammatory component, as shown by surprisingly normal albumin levels." (PMID 21542928, 2011). "Conversely, other studies have shown that serum visceral proteins (albumin and prealbumin) are not reliable predictors of nutrient deficiencies and should not be used as the sole criterion for guiding nutritional therapy, particularly in cohorts consisting mainly of patients with anorexia nervosa." (PMID 41515189, 2025). "In well-studied diseases related to low appetite and decreased caloric intake, such as anorexia nervosa and ARFID, serum albumin and protein concentrations are often normal or even elevated compared to controls." (PMID 39408368, 2024). "GDF15 correlated with low albumin and high levels of alanine aminotransferase in the anorectic group but not in the control group, which supports that GDF15 in patients with anorexia nervosa may be liver-derived." (PMID 36545337, 2022). "In addition, both low albumin and elevated alanine aminotransferase are markers for evaluating liver function, indicating that hepatic “stress” mediates an increase in plasma GDF15 in patients with anorexia nervosa." (PMID 36545337, 2022). "Similarly, a case-control study that compared 14 anorexia nervosa patients with 15 healthy subjects reported that serum albumin levels did not vary in individuals with anorexia nervosa compared with controls during a follow-up of one year." (PMID 27174435, 2016).